REN (renin)
Diseases named in the same sentence as REN in open-access papers (continued):
Sharing a sentence is not in itself a finding about the gene and the disease.
endothelial dysfunction (continued). "The development of CRS type 4 leads to neurohormonal activation (mainly of the renin–angiotensin–aldosterone system), hemodynamic changes, chronic inflammation, oxidative stress, and endothelial dysfunction, which ultimately result in damage and fibrosis of the heart and vessels." (PMID 39857818, 2025). "In addition to promoting respiratory malignancies, tobacco smoke also stimulates the renin–angiotensin system, and exacerbates cardiovascular injury through oxidative stress, endothelial dysfunction, and chronic inflammation." (PMID 40924729, 2025). "This synergistic interaction may be explained by shared pathophysiological mechanisms between MetS and RHF, such as renin-angiotensin system activation and endothelial dysfunction." (PMID 41164368, 2025). "The accumulation of adipose tissue contributes to endothelial dysfunction, peripheral vascular resistance, and activation of the renin-angiotensin-aldosterone system, mechanisms that increase activation of the renin-angiotensin-aldosterone system, which increases blood pressure." (PMID 40094070, 2025). "The TyG index is a validated surrogate marker for hepatic and peripheral insulin resistance, which contributes to CKD pathogenesis through glomerular hyperfiltration, activation of the renin–angiotensin–aldosterone system, endothelial dysfunction, and pro-inflammatory and pro-fibrotic mechanisms." (PMID 41010511, 2025). "Activation of the local tissue renin–angiotensin system is well-known as playing pivotal roles in exacerbating atherosclerosis via many mechanisms, including endothelial dysfunction and proinflammatory gene expression, which ultimately leads to cardiovascular and renal events." (PMID 40362650, 2025). "Several mechanistic pathways are implicated in the pathogenesis of this phenomenon, including volume and sodium overload, overactivity of sympathetic nervous system and renin–angiotensin–aldosterone system, endothelial dysfunction,and increased arterial stiffness." (PMID 38710537, 2024). "Various mechanisms might contribute to kidney injuries in older adults hypertensive patients, including the renin-angiotensin-aldosterone system, oxidative stress, endothelial dysfunction, and genetic and epigenetic factors." (PMID 38983263, 2024). "The pathophysiology of HRE is multifactorial and includes higher arterial stiffness, vascular peripheral resistance, worse endothelial dysfunction, increased activation of the sympathetic nervous and renin-angiotensin-aldosterone systems, and enhanced chronic inflammation." (PMID 39797099, 2024). "Endothelial dysfunction is common in CKD in which uremic toxins, insulin resistance, vascular calcification, dyslipidemia, anemia, and renin–angiotensin activation are proposed to cause chronic inflammation and oxidative stress and promote atherogenesis and arteriosclerosis." (PMID 38399507, 2024). "Obesity increases arterial stiffness due to endothelial dysfunction, impaired vascular smooth muscle cell function, IR, elevated cholesterol, C-peptide levels, fat distribution, adipose tissue-related renin-aldosterone-angiotensin system, and increased leptin levels." (PMID 39335575, 2024). "Moreover, other crystal-independent mechanisms have been proposed, including renal vasoconstriction mediated by endothelial dysfunction and activation of the renin-angiotensin system, etc.." (PMID 39135624, 2024). "The loss of β-cells may lead to increased oxidative stress, activation of the renin-angiotensin system, release of inflammatory cytokines, and endothelial dysfunction, thereby accelerating atherosclerosis and increasing the risk of cardiovascular disease." (PMID 39720249, 2024). "The continued decline in renal function progresses to CKD, leading to volume overload, activation of the renin–angiotensin–aldosterone system, sympathetic hyperactivity, reduced sodium excretion salt retention, and endothelial dysfunction, which in turn leads to elevated blood pressure." (PMID 39400628, 2024).
endothelial dysfunction (continued). "Free-fatty-acid-mediated endothelial dysfunction involves several mechanisms, including impaired insulin signaling and nitric oxide production, oxidative stress, inflammation, and the activation of the renin–angiotensin system and apoptosis in the ECs." (PMID 39770410, 2024). "In addition, ROS inactivate both NO production and the renin–angiotensin system, leading to endothelial dysfunction and tubular damage." (PMID 38398435, 2024). "In addition, certain studies have indicated that HUA can enhance atherosclerosis development through inflammation, endothelial dysfunction, vascular smooth muscle cell proliferation, oxidative stress, and renin-angiotensin-aldosterone system activation." (PMID 39108673, 2024). "BMI might be a cause of HTN and other cardiovascular disease by stimulating the renin-aldosterone system and endothelial dysfunction." (PMID 37616271, 2023). "Obesity induces pathological alterations in the heart-related renin-angiotensin-aldosterone system, which increases the secretion of aldosterone and promotes myocardial fibrosis, platelet aggregation, and endothelial dysfunction, leading to cardiomyocyte hypertrophy and apoptosis." (PMID 36614227, 2023). "Moreover, IR usually leads to increased systemic and tissue inflammation, oxidative stress, endothelial dysfunction and renin-angiotensin-aldosterone system activation, thereby resulting in cell damage and affecting the longevity of individual's life." (PMID 36860689, 2023). "The exact mechanism explaining the association between MetS and renal disease has not been completely clarified; however, the suggested pathophysiological factors include IR, oxidative stress, endothelial dysfunction, hyperfiltration, and renin–angiotensin–aldosterone-system activation." (PMID 37670399, 2023). "These conditions may therefore constitute a risk of mortality, while high levels of vitamin D may reduce signal between renin, angiotensin and aldosterone, improve endothelial dysfunction and modulate immune function." (PMID 37380964, 2023). "This could lead to exacerbation of the pre-existing endothelial dysfunction, as well as a further dysregulation of the renin–angiotensin system and the immune system in these patients, which could lead to a more severe state of the infection." (PMID 37958866, 2023). "Several mechanisms were previously postulated in order to offer a reasonable explanation for its casual role, such as inflammatory response, renal microcirculation vascular changes and renin-angiotensin system activation, endothelial dysfunction, oxidative stress and subclinical atherosclerosis." (PMID 36996140, 2023). "Moreover, the blockade of angiotensin II in the renin-angiotensin system contributes to difficulties in the expression of angiotensin I and add up to endothelial dysfunction, damages organs, and consequently, increases the chance of stroke." (PMID 37109156, 2023). "Emerging studies allege a new hypothesis concerning UA and renal impairment involving a pro-inflammatory status, endothelial dysfunction, and excessive activation of renin–angiotensin–aldosterone system (RAAS)." (PMID 35328614, 2022). "The increased blood pressure in these hypothyroid patients might result from the increase of systemic vascular resistance, endothelial dysfunction, and low renin level." (PMID 35909519, 2022). "FFA-mediated endothelial dysfunction involves several mechanisms, including dysregulated production of nitric oxide and cytokines, metaflammation, oxidative stress, inflammation, activation of the renin-angiotensin system, and apoptosis." (PMID 34529222, 2022). "Other current pathogenesis incriminated in the onset and progression of already mentioned diseases are epithelial-to-mesenchymal transition in renal tubular cells, renal vasoconstriction mediated by endothelial dysfunction, and activation of renin-angiotensin system (RAAS)." (PMID 35328614, 2022).
endothelial dysfunction (continued). "There are several mechanisms that are involved in the development of arterial stiffness such as extracellular matrix alterations, vascular smooth muscle cell stiffening, endothelial dysfunction, renin-angiotensin-aldosterone system signaling, oxidative stress, and inflammation." (PMID 35873099, 2022). "Still, they may include a hypercoagulability state, inflammation and cytokine storm, endothelial dysfunction, and an aberrant renin-angiotensin-aldosterone (RAAS) axis due to the binding of SARS-CoV-2 to the endothelial ACE-2." (PMID 35329864, 2022). "Sleep disorder can lead to inflammation, oxidative stress, endothelial dysfunction, increased sympathetic tone, activation of the renin-angiotensin system, circadian timing dysfunction and subsequent systemic and intraglomerular pressure, which hereby adversely affects kidney function." (PMID 36440426, 2022). "The imbalance of ROS and NOS leads to endothelial dysfunction and induces plasma renin activity." (PMID 35055342, 2022). "Insulin resistance may induce renal sodium retention, activate the renin–angiotensin system and enhance the sympathetic nervous system activity, and promote endothelial dysfunction, and increase peripheral and renal vascular resistance." (PMID 36504986, 2022). "The pathophysiology of HF is heterogeneous and results from an initial harmful event in the heart that promotes neurohormonal changes such as autonomic dysfunction and activation of the renin-angiotensin-aldosterone system, endothelial dysfunction, and inflammation." (PMID 35893744, 2022). "The reason may be because, first, IPO can reduce vascular inflammation and endothelial dysfunction, and inhibit the excessive activation of the renin–angiotensin–aldosterone system." (PMID 33731005, 2021). "The mechanisms of uric acid-induced renal injury may involve inflammation, endothelial dysfunction, oxidative stress, mitochondrial dysfunction and activation of renin-angiotensin system." (PMID 34187292, 2021). "Different studies have highlighted complement activation (e.g. the C5aR1 axis), platelet activation, immune-mediated thrombotic mechanisms, endothelial dysfunction, antiphospholipid antibody, and renin-angiotensin system dysregulation as important actors of COVID-19-associated coagulopathy." (PMID 34422854, 2021). "Insulin resistance increases tissue inflammation and reactive oxygen species production, thus resulting in endothelial dysfunction, inappropriate activation of the renin angiotensin aldosterone system, increased sympathetic nervous system activity, and abnormal sodium handling by the kidney." (PMID 34251744, 2021). "The authors suggest that although ACE2 reduction would decrease the virus infectivity, a dysregulated renin-angiotensin system due to ACE2 reduction may exacerbate endothelial dysfunction, leading to endothelitis." (PMID 34204890, 2021). "Low vitamin D levels may activate the renin–angiotensin system, give rise to inflammatory reactions and result in endothelial dysfunction." (PMID 33498709, 2021). "Factors that may favour the association between cardiovascular disease and mortality in COVID-19 are endothelial dysfunction, myocardial depression, renin–angiotensin–aldosterone system disorder, or coagulation imbalances." (PMID 35011795, 2021). "First, AKI causes sustained oxidative stress and promotes dysregulation of the renin-angiotensin-aldosterone system, which induces macrophage infiltration, cardiac inflammation, and myocardial fibrosis, and leads to endothelial dysfunction and cardiac fibrosis as well as ventricular dysfunction." (PMID 34646162, 2021). "The renin-angiotensin system also could be involved in endothelial dysfunction in COVID-19 patients." (PMID 33123154, 2020).
endothelial dysfunction (continued). "Mechanistically, serving as functional receptors for SARS-CoV-2, angiotensin-converting enzyme 2 (ACE2) mediates SARS-CoV-2 infection of endothelial cells (ECs) directly, leading to endothelial dysfunction and dysregulation of the renin-angiotensin system (RAS)." (PMID 33553222, 2020). "The pathophysiology is not definitively known, but also in this case, it is hypothesized to be related to endothelial dysfunction, inflammation, and abnormalities in the renin-angiotensin-aldosterone system." (PMID 32008434, 2020). "Besides, SUA has a direct effect on the activation of the local renin-angiotensin system, endothelial dysfunction, smooth muscle cell proliferation, and decreasing nitric oxide production." (PMID 33330657, 2020). "Several studies suggested the relationship between UA and pathological process such as oxidative stress, systemic inflammation, and activation of the renin-angiotensin system, which further lead to endothelial dysfunction, vascular smooth muscle cells proliferation and increased arterial stiffness." (PMID 31941543, 2020). "Excess UA turned out to be closely related to endothelial dysfunction, oxidative stress, inflammation and activation of the renin-angiotensin system, which may lead to cardiovascular diseases." (PMID 31388342, 2019). "As a neurosteroid, vitamin D plays a vital role in preventing vascular injury through the mechanism of inhibiting the renin-angiotensin-aldosterone system and atherogenesis, lowering blood pressure, reduction in endothelial dysfunction, and neuroprotective actions in stroke." (PMID 31315602, 2019). "As we already know, the pathogenesis of diabetic nephropathy has complex mechanisms including the effect of high glucose, endothelial dysfunction inflammation, renin-angiotensin system activation, reactive oxygen species, increase of advanced glycation end-product, and glomerular hyperfiltration." (PMID 30736343, 2019). "Several recent studies demonstrated that hyperuricemia could worsen the injury of the renal tubule via pro-inflammatory pathways involving activation of the renin-angiotensin system, chemokine expression, and endothelial dysfunction." (PMID 31295810, 2019). "Blood UA can interfere with the synthesis of nitric oxide, inhibit nitric oxide bioavailability, activate the renin-angiotensin system, promote vascular smooth muscle cell proliferation and platelet aggregation, and eventually lead to the endothelial dysfunction." (PMID 30647801, 2018). "Other contributing mechanisms may include overactivity of the renin-angiotensin-aldosterone system, endothelial dysfunction, and systemic inflammation." (PMID 29470498, 2018). "In the kidneys, however, UA may activate the renin-angiotensin-aldosterone system, which is an important source of ROS responsible for endothelial dysfunction and mesenchymal-epithelial transformation." (PMID 30103431, 2018). "Dyslipidemia can take part of the development and progression of renal disease in non-exercising conditions (i.e. lipid nephrotoxicity) through inflammatory stress, oxidative stress, endoplasmic reticulum stress, endothelial dysfunction, and activation of the renin–angiotensin system." (PMID 30349484, 2018). "In addition, sympathetic stimulation, renin-angiotensin-aldosterone system activation, inflammation, oxidative stress and endothelial dysfunction also contribute to alterations of RUV by renal fibrosis." (PMID 29554877, 2018). "Different pathophysiological processes involved in SAH are now known to be regulated by miRNAs, including endothelial dysfunction, dysregulation of vascular smooth muscle cells (VSMCs), the increase of sympathetic system activity, and alterations in renin-angiotensin-aldosterone system (RAAS)." (PMID 30445764, 2018).
endothelial dysfunction (continued). "Low levels of vitamin D have been reported to be associated not only with obesity and insulin resistance but also with glucose intolerance, dyslipidemia, increased renin gene transcription, endothelial dysfunction, proliferation of vascular smooth muscle cells, thrombogenecity and inflammation." (PMID 29149839, 2017). "Studies showed that endothelial dysfunction, oxidative stress, inflammation and the activation of renin-angiotensin system may be involved in the hyperuricemia induced kidney injury." (PMID 29340054, 2017). "The main acute physiological outcomes of OSAS are intermittent hypoxia, intrapleural pressure changes, and sleep fragmentation which induce endothelial dysfunction, sympathetic activation, renin-angiotensin-aldosterone system activation, and increased oxidative stress." (PMID 29147581, 2017). "Consequently, it affects modulation of the renin-angiotensin-aldosterone system, and can limit endothelial dysfunction in this way." (PMID 29258230, 2017). "Furthermore, the activated renin-angiotensin-aldosterone system plays an important role in endothelial dysfunction and myocardial remodeling in the progress of heart failure." (PMID 27340403, 2016). "Low levels of vitamin D may lead to endothelial dysfunction, inflammation, activation of the renin-angiotensin system, vascular smooth muscle cell proliferation and CAC." (PMID 27171378, 2016). "As part of a holistic molecular genetic medicine approach in this study, we evaluated the incidence of CV risk factors, including impaired glucose intolerance, hyperlipidemia, an activated renin-aldosterone system, endothelial dysfunction, and high IMT among children with WS." (PMID 26384008, 2015). "Uric acid may contribute to kidney fibrosis mainly by inducing inflammation, endothelial dysfunction, oxidative stress, and activation of the renin-angiotensin system." (PMID 26783458, 2015). "These patients often develop multiple alterations at the vascular level, leading to endothelial dysfunction, coagulation abnormalities, insulin resistance, hyperhomocystinaemia and activation of the sympathetic nervous system, as well as the renin–angiotensin and aldosterone system." (PMID 25210973, 2014). "In fact, low vitamin D may lead to endothelial dysfunction, inflammation, activation of the renin-angiotensin system, vascular smooth muscle cell proliferation and vascular calcification and myocardial infarction." (PMID 24748388, 2014). "Uric acid and xanthine oxidase may contribute to kidney fibrosis mainly by inducing inflammation, endothelial dysfunction, oxidative stress, and activation of the renin-angiotensin system." (PMID 24877124, 2014). "For example, hyperuricemia can induce endothelial dysfunction, glomerular hypertrophy, afferent arteriolar wall thickening, vascular smooth muscle hypertrophy, inhibit endothelial nitric oxide production and activation of the renin-angiotensin system." (PMID 23637835, 2013). "Nevertheless, hyperactivity of renin-angiotensin system, endothelin, sympathetic activation, and inflammation may also contribute to oxidative stress and endothelial dysfunction." (PMID 22518280, 2012). "Other systems contribute to this imbalance such as renin-angiotensin and ET-1 which may participate in the pathogenesis of endothelial dysfunction." (PMID 22518280, 2012). "In the vascular endothelium, ROS activates the renin–angiotensin system and reduces nitric oxide (NO) bioavailability by promoting NO inactivation and uncoupling of endothelial nitric oxide synthase (eNOS), resulting in impaired vasodilation and endothelial dysfunction." (PMID 41596333, 2026). "In addition, elevated uric acid levels could lead to endothelial dysfunction and activation of the renin–angiotensin system." (PMID 39139864, 2024).